Y_RNA (Y RNA )
Gene: Miscellaneous RNA gene on chromosome 14 (31,258,608 to 31,258,709, reverse strand). Ensembl gene ENSG00000199291.
Homologues: Orthologues: chimpanzee Y_RNA (96% identical), macaque Y_RNA (94% identical), guinea pig Y_RNA (93% identical). Paralogues in human: RNY3 (96% identical), RNY3P1 (95% identical), Y_RNA (95% identical), Y_RNA (94% identical), Y_RNA (93% identical), Y_RNA (92% identical), Y_RNA (91% identical), RNY3P11 (90% identical), Y_RNA (90% identical), RNY3P14 (89% identical), Y_RNA (89% identical), RNY3P16 (88% identical), and 100 more.